CTLA4 (cytotoxic T-lymphocyte associated protein 4)
Diseases named in the same sentence as CTLA4 in open-access papers (continued):
Sharing a sentence is not in itself a finding about the gene and the disease.
glioma (continued). "This suggests that the expression pattern and clinical characteristics of CTLA-4 in glioma are related to tumour severity." (PMID 38660136, 2024). "The high CKS expression predicts poor survival for many malignancies, and the co-expression of CKS and some immune checkpoints, including PD-1 and CTLA4, has been discovered in glioma." (PMID 38462627, 2024). "In glioma, CTLA-4 expression is significantly correlated with both the WHO grade and isocitrate dehydrogenase (IDH) status, indicating its varied roles in tumor biology and patient prognosis." (PMID 38342925, 2024). "Elevated CTLA-4 expression in high-grade gliomas compared to low-grade gliomas suggests a positive correlation between CTLA-4 expression and cancer severity." (PMID 38275876, 2024). "Anti-CTLA-4 therapies, designed to block CTLA-4 synthesis and thereby boost T cell activity, have shown variable effectiveness in glioma models." (PMID 38342925, 2024). "Liu and colleagues examined 1024 glioma patients and found higher CTLA4 expression in aggressive gliomas, particularly those with higher grades, IDH-wild type status, and the mesenchymal molecular subtype." (PMID 39409893, 2024). "The expression of the more well-known immune-related targets in glioma, such as CTLA4, PDCD1 (PD-1), CD274 (PD-L1), LAG-3, and CD47, was then examined." (PMID 38396140, 2024). "It has been shown that therapeutic inhibition of IDO1, CTLA-4, or PD-L1 significantly reduced the number of tumor-infiltrating T cells and significantly prolonged the survival in a mouse model of glioma." (PMID 39502752, 2024). "Previous studies have demonstrated that immune checkpoint molecules including PD-L1, CTLA-4 and IDO are associated with immune evasion in glioma cells." (PMID 38846954, 2024). "After that, we found that 6 immune checkpoints (CD274, CTLA4, LAG3, LGALS9, PDCD1, and PDCD1LG2) were significantly upregulated in the high-glioma-risk group, while RDH5, RDH10 and DHRS3 simultaneously have a substantial positive connection with PDCD1LG2." (PMID 39465792, 2024). "In a murine glioma model, CTLA-4 blockade was shown to enhance anti-tumor immunity via improved CD4+ T cell function and resistance to Foxp3+ Tregs." (PMID 36768342, 2023). "Using the CGGA male dataset, the expression profile of A2AR was then compared to the expression of three critical immune checkpoints (PD-1, PD-L1, CTLA-4) known to be highly expressed in gliomas." (PMID 37047660, 2023). "All six of the most critical ICGs that were examined, including CD274, CTLA4, HAVCR2, IDO1, PDCD1, and PDCD1LG2, exhibited a significant positive correlation with the risk scores in glioma samples." (PMID 36845382, 2023). "Immune checkpoint blockers, such as CTLA-4 and PD-1/PD-L1 inhibitors, promote the development of tumor immune response to glioma, enhancing the unique role of the tumor immune system response." (PMID 36714030, 2023). "Nevertheless, checkpoint inhibitors, such as anti-CTLA4, anti-PD-1 and anti-PD-L1, have poor clinical efficacy in glioma." (PMID 37325664, 2023). "In an advanced-glioma mouse model, combination of intratumor IL-12 with anti-CTLA-4 successfully led to tumor eradication, compared with either of the monotherapies." (PMID 37444531, 2023). "We found that the expression level of REST protein was significantly positively correlated with PD1, PD-L1, and CTLA-4 in glioma, which was adjusted by purity (P < 0.001)." (PMID 36810892, 2023). "REST expression was positively correlated with infiltration of immune cells and the expression of immune checkpoints such as PD1/PD-L1 and CTLA-4 in glioma." (PMID 36810892, 2023). "A previous study showed elevated CTLA4 expression in glioma patients correlated with cancer progression." (PMID 37152037, 2023). "In general, most immune checkpoints (including PD-1, TIM-3, CD96, PDCD1, IDO1, PDCD1LG2, and CTLA-4) were highly expressed in glioma cells." (PMID 36778644, 2023).
glioma (continued). "The anti-therapy aimed at CTLA-4 seems less successful in gliomas because of complicated reasons, including the blood-brain barrier and a lack of guiding biomarkers of the blockade." (PMID 36776876, 2023). "Glioma cells can evade immune surveillance through activation of immune checkpoint ligands such as PD-1, CTLA-4, and IDO." (PMID 37705736, 2023). "Though the anti-CTLA-4 antibody, ipilimumab, has been tested and found effective in treating several cancers, preclinical glioma models have brought unsatisfying results as to anti-CTLA-4 monotherapy." (PMID 37444531, 2023). "Similar to TIMER data analysis, there was significant positive correlation of REST with PD1, PD-L1, or CTLA-4 in glioma by GEPIA2 (P < 0.001)." (PMID 36810892, 2023). "The same study using a GL261 glioma mouse model showed complete tumor regression using a sequential regime of an anti-CTLA-4 antibody and a whole-tumor-cell vaccine." (PMID 37444531, 2023). "Several studies demonstrated that the expression of CTLA-4 is positively correlated with disease progression in patients with glioma." (PMID 37274252, 2023). "Most clinical trials investigating the use of CTLA-4 and PD-1 inhibitors in glioma are currently ongoing, with only a few published findings, and none achieving significant efficacy." (PMID 37405952, 2023). "Other studies combining anti-PD1 with anti-CTLA-4 in GL261 glioma mouse models showed decreased tumor growth and improved symptom-free survival." (PMID 37444531, 2023). "Correlation analysis revealed that the risk score was closely related to the expression levels of CD3, CD8, PD-L1, and CTLA4 in glioma patients." (PMID 35571034, 2022). "A preclinical study in a mouse model of glioma also evaluated the combination of SRT (single dose of 10 Gy) with CTLA-4 blockade and the co-stimulatory molecule 4-1BB (CD137)." (PMID 35740435, 2022). "In glioma models, miR-138 inhibited CTLA-4 and PD-1, leading to significant regression of subcutaneous tumors." (PMID 36012588, 2022). "Preclinical research has suggested that the combination of CTLA-4 and IL-12 blockade elicits T cell-mediated glioma rejection in a syngeneic murine model of GBM." (PMID 35428347, 2022). "Immune checkpoint blockades that target CTLA-4 and PD-1/PD-L1 have shown some promise against glioma, but only a fraction of patients respond to treatment." (PMID 35559020, 2022). "According to our constructed GSRS, the expression of vital ICPs (PD-L1, PD-1, and CTLA4) and TMB was significantly correlated with a risk score, and these indicated that high-risk gliomas were more likely to be sensitive to ICB therapy." (PMID 36405708, 2022). "The upregulation of mir-155 accelerates pediatric high grade glioma invasion by CTLA-4 and PD-L1 activation." (PMID 35326280, 2022). "Immune checkpoint blockade such as programmed cell death 1 ligand (PD-L1), indolamine 2,3-dioxygenase (IDO), and cytotoxic T lymphocyte associated antigen 4 (CTLA4), appears to be a potential therapeutic treatment for glioma." (PMID 35884551, 2022). "Upregulation of some immune checkpoints, such as CD27, CD274 (PD-L1), CTLA4, IDO1, and PDCD1 (PD-1), were reported to be associated with poor survival and recurrence in gliomas." (PMID 35874989, 2022). "Tests primarily targeting PD-1/PD-L1 or CTLA-4 immune checkpoint inhibitors have been conducted in glioma." (PMID 36065303, 2022). "There is accumulating evidence that immune cells are inhibited in the glioma microenvironment through a variety of mechanisms, including the presence of immune checkpoints such as PD-1/PD-L1 and CTLA-4." (PMID 36466873, 2022). "Immune checkpoint inhibitors, particularly treatments such as anti-PD-1/PD-L1 and CTLA-4, are effective against a wide range of tumors but have performed poorly in clinical trials in glioma." (PMID 36291283, 2022). "Previous studies have identified different immune checkpoint molecules in gliomas, such as CTLA-4, TIM-3, PD-1, CD48, and LAG3." (PMID 35832194, 2022).
glioma (continued). "Previous studies have shown that therapeutic inhibition of IDO, CTLA-4, or PD-L1 in mouse glioma models significantly reduces the number of tumor-infiltrating Treg cells and substantially improves long-term survival." (PMID 35547808, 2022). "Those gliomas with high PuMRS would have more immune cell infiltration and overexpress several immunotherapy targets (PD-1, PD-L1, B7-H3, and CTLA4)." (PMID 36438805, 2022). "Results of the present study demonstrated an improved immune response compared with traditional PDL1/CTLA4 immune checkpoints in patients with glioma." (PMID 35719378, 2022). "In fact, in glioma case different immune checkpoint molecules have been described such as CTLA-4, PD-1, TIM-3, and LAG-3; each of these receptors has corresponding ligands." (PMID 34305910, 2021). "Anti-CTLA-4 therapy has been approved for several cancers, extending survival of glioma-bearing mice, and in combination with anti-PD-1 therapy, shown eradication of tumors in a majority of mice." (PMID 34298615, 2021). "At last, VISTA mRNA expression levels appeared to be the highest in all glioma cases (low and high grade) when compared to those of other critical immune checkpoints, Tim-3, PD-1, CTLA-4, LAG-3 and TIGIT (p < 0.0001)." (PMID 34728682, 2021). "The expression of CTLA-4 in glioma specimens of patients who underwent neurosurgical resection indicated that higher CTLA-4 expression in the tumor microenvironment resulted in greater immune cell infiltration and correlated with a shorter overall survival." (PMID 34298735, 2021). "The efficient delivery of ICIs to the glioma is expected to directly disrupt the PD-1/PD-L1 or CTLA-4/B7-1 complex formation in the tumor, resulting in the activation of brain local immune response and leading to the improved survival of glioma mice." (PMID 33535531, 2021). "Studies have reported that the triple combination of anti-CTLA-4, anti-PD-1, and G47Δ-mIL12 was able to cure most mice of glioma." (PMID 34054811, 2021). "Immune checkpoint was another important target for glioma treatment and some immunotherapy drugs had entered clinical trials, inhibition of PD‐L1, CTLA4, Indoleamine 2,3‐dioxygenase (IDO) was included." (PMID 34482648, 2021). "Currently, clinical trials of anti-CTLA-4 (ipilimumab) and anti-PD-1 (nivolumab) are being performed in patients with glioma, testing the safety, toxicities, and efficacy." (PMID 34305910, 2021). "Although PD-1 and CTLA-4 antibodies have achieved a sustained response in some patients, most patients with glioma demonstrated poor responses to them." (PMID 34267752, 2021). "The results from TIMER website illustrated that there was a significant positive correlation between MK3 expression and PD-1, PD-L1, and CTLA-4 in glioma, which was adjusted by tumor purity." (PMID 34938665, 2021). "Additional studies are needed to further explore the molecular mechanisms mediating CTLA-4 expression in gliomas and responses to anti-CTLA-4 therapy." (PMID 31911758, 2020). "Based on our findings in TCGA and CGGA databases, higher expression of CTLA-4 was observed in higher grades of glioma, highlighting the possible relationship of CTLA-4 expression with poorer prognosis." (PMID 31911758, 2020). "With so many clinical trials, a comprehensive analysis of CTLA-4 expression will be required to identify the enrichment criteria of CTLA-4 in glioma clinical trials." (PMID 31911758, 2020). "Targeting CTLA-4 in glioma models with anti CTLA-4 antibodies proved useful in reversing immune evasion." (PMID 32765498, 2020). "Combination ICB therapy targeting PD-1 and CTLA-4 suppressed tumor growth of established syngeneic orthotopic mouse gliomas." (PMID 32071302, 2020). "To further characterize the relationship between CTLA-4 and TCGA-defined molecular subtypes, we measured CTLA-4 levels in different glioma subtypes." (PMID 31911758, 2020).
glioma (continued). "CTLA-4 expression in mesenchymal-molecular subtype glioma was significantly higher than in the other three subtypes in both databases." (PMID 31911758, 2020). "Here, we investigate resistance mechanisms to anti-PD-1 and anti-CTLA-4 therapy in syngeneic hypermutated experimental gliomas and show a clear dichotomy and acquired immune heterogeneity in ICB-responder and non-responder tumors." (PMID 32071302, 2020). "Several studies of immune checkpoint inhibitors targeting CTLA-4 have demonstrated promising benefits in patients with glioma." (PMID 31911758, 2020). "A variety of clinical trials targeting programmed death (PD)-1/PD-ligand 1 (PD-L1), and cytotoxic T-lymphocyte antigen (CTLA)-4 have been investigated in patients with glioma to promote the robust antitumor T cell response." (PMID 31911758, 2020). "MiR-138 exerts anti-glioma efficacy by targeting the immune checkpoint molecules CTLA-4 and PD-1 by inhibiting tumor-infiltrating Tregs." (PMID 32122338, 2020). "We expect that our findings will help facilitate the development of potential anti-CTLA-4 treatments in glioma." (PMID 31911758, 2020). "Further protein expression pattern of CTLA-4 in glioma also suggested that CTLA-4 expression was detected in high-grade glioma samples." (PMID 31911758, 2020). "We investigated the protein level of CTLA-4 in human glioma samples, extracted genetic and clinical data from 1024 glioma patients to characterize CTLA-4 expression and its relationship with immune functions in gliomas." (PMID 31911758, 2020). "Patients with glioma with lower CTLA-4 expression exhibited significantly longer OS compared with patients with glioma with higher CTLA-4 expression in both TCGA and CGGA databases." (PMID 31911758, 2020). "We also validated our findings in CGGA database; similar to the results from TCGA database, higher expression of CTLA-4 was observed in grade IV glioma compared with that in grade II and grade III glioma (p < 0.01)." (PMID 31911758, 2020). "The first large phase III trial of ipilimumab (a CTLA-4 inhibitor) plus nivolumab (a PD-1 inhibitor) in recurrent World Health Organization (WHO) grade IV glioma (glioblastoma) (NCT02017717) was initiated in 2014." (PMID 31911758, 2020). "In summary, we investigated the associations of CTLA-4 expression with clinicopathological findings and IDH mutation status in gliomas." (PMID 31911758, 2020). "The effectiveness that clinical trials of anti-PD-1 and anti-CTLA-4 monotherapy for glioma patients were limited." (PMID 31428092, 2019). "Although the list of various immune checkpoints is growing fast, the most commonly studied molecules are PD-1 and CTLA-4 which have already demonstrated promising benefits in patients with glioma in numerous studies." (PMID 30619286, 2018). "Tumor-infiltrating immune cells of glioma patients exhibit significant expression of CTLA-4 (particularly for CD4+ effector T cells and Tregs)." (PMID 30619286, 2018). "In particular the possibility of targeting at the same time different ICs was pre-clinically tested in an animal model were inhibitors against IDO, CTLA-4 and PD-L1 were combined and showed persistent and significant antitumor effects in glioma-bearing mice." (PMID 30406030, 2018). "•PD-L1, PD-L2, and CTLA4 DNA methylation in lower-grade gliomas is inversely correlated with mRNA expression levels." (PMID 29396294, 2018). "A study in glioma patients showed that CTLA-4 is highly expressed on T cells, specifically the effector CD4+T cells and Tregs." (PMID 27756892, 2017). "In vivo, miR-138 treatment potently suppresses glioma growth, decreasing the ratio of intratumoral Treg, reducing the expression of CTLA-4 and PD-1, and leading to a 43% increase in the median survival time." (PMID 27756892, 2017).
glioma (continued). "In glioma cells injected into mouse striatum, the combination of CTLA-4 blockade, 4-1BB activation (4-1BB, when activated, stimulates CD8+ T-cell proliferation), and radiotherapy significantly improved overall survival compared to a single modality alone." (PMID 28730140, 2017). "The importance of CTLA-4 promoted T-cell immune reactivity for glioma defense has been elaborated both preclinically and clinically." (PMID 28977847, 2017). "For the vast majority of ESCC cases, CTLA-4-positive cells were scattered evenly throughout the specimen, in a similar form to that observed in glioma and ovarian cancer." (PMID 27050369, 2016). "In an experimental glioma model, anti-CTLA-4 mAb procured an 80% long-term survival rate, concurrent with enhanced proliferation of CD4+ CD25− T cells and resistance to suppression by Treg cells." (PMID 26217588, 2015). "Anti-CTLA-4 antibodies have shown potential therapeutics for gliomas, and combining sequential immunotherapy with GM-CSF expressing irradiated glioma cell vaccine synergistically prolongs survival in mice-bearing gliomas." (PMID 25009822, 2014). "Conversely, murine intracranial SMA-560 gliomas treated with anti-CTLA-4 antibodies as a monotherapy elicited long-term survival in 80% of treated animals." (PMID 25013914, 2014). "Combination therapy with 4-1BB activation and CTLA-4 blockade in the setting of focal radiation therapy improves survival in an orthotopic mouse model of glioma by a CD4+ T cell dependent mechanism and generates antigen-specific memory." (PMID 25013914, 2014). "In our preclinical study, we have shown that triple therapy combining RT with anti-4-1BB and anti-CTLA-4 antibodies confers long-term survival in a murine GL261 glioma model." (PMID 25013914, 2014). "Using the same model, vaccination with granulocyte-macrophage colony-stimulating factor (GM-CSF)-expressing whole glioma cell vaccination followed by CTLA-4 blockade has been demonstrated to significantly improve survival." (PMID 23720663, 2013). "In the GL261 mouse model of glioma, combining Treg depletion with CTLA-4 neutralization boosts glioma-specific Tc and Tconv effector T cell responses, while also increasing anti-glioma IgG2A antibody titers; ultimately resulting in complete tumor rejection." (PMID 23720663, 2013). "In the SMA-560 mouse model of glioma, neutralization of CTLA-4 with monoclonal antibody, 9H10, confers a long-term survival benefit in 80% of treated mice with re-establishment of normal CD4 counts concomitant with a decreased Treg fraction." (PMID 23720663, 2013). "The inhibitory costimulatory molecules, CTLA-4 and PD-1, are known to impact anti-tumor immune responsiveness in murine tumor models, including gliomas." (PMID 22485134, 2012). "Depletion of Tregs using immunoglobulins against CTLA4 has been found to improve survival in mouse models of glioma." (PMID 18431473, 2008). "CTLA-4 suppresses T-cell priming; elevated in glioma TME contributes to immune escape." (PMID 41346390, 2025). "Active glioma Tregs can bind to CD80/CD86 via CTLA-4, suppressing T cell activity." (PMID 40071070, 2025). "Mice were injected with U-87 MG or GL261 glioma cells in their flanks and were subsequently treated with one of two ulRFE cognates: A1A, inspired by paclitaxel, or A2, based on murine siRNA targeting CTLA4 + PD1." (PMID 38594769, 2024). "Indeed, G47Δ-mIL12, anti-CTLA4, and anti-PD-1 triple therapy showed surprising results, curing most mice in glioma models and outperforming G47Δ-mIL12, anti-CTLA4, and anti-PD-1 alone in prolonging survival." (PMID 39451566, 2024). "Furthermore, a robust connection emerged between CTLA4 expression and immune cell infiltration within the glioma microenvironment, signifying potential effects on antitumor immune responses." (PMID 39409893, 2024). "Notably, we also found that 6 immune checkpoints were significantly upregulated in the high-glioma-risk group, including CD274, CTLA4, LAG3, LGALS9, PDCD1, and PDCD1LG2." (PMID 39465792, 2024).